EPHA2 (EPH receptor A2)
Diseases named in the same sentence as EPHA2 in open-access papers (continued):
Sharing a sentence is not in itself a finding about the gene and the disease.
pancreatic cancer (continued). "Exosome-derived EphA2 has been suggested as a potential serum biomarker for pancreatic cancer diagnosis." (PMID 37712876, 2023). "The nPES assay for ephrin type-A receptor 2 (EphA2)-EVs, a pancreatic cancer EV biomarker, was able to distinguish pancreatic cancer patients from pancreatitis patients." (PMID 35501802, 2022). "Another study reported the development of a nano-plasmon enhanced scattering (nPES) assay for the detection of ephrin type-A receptor 2 (EphA2) protein pancreatic cancer specific EV biomarker." (PMID 35880114, 2022). "It appears that exosomes containing Eph receptor A2 (EphA2) are able to transfer metastatic potential to pancreatic cancer cells and promote their invasion." (PMID 35765040, 2022). "The specificity and sensitivity of EphA2 in sEV as a possible biomarker has shown to be extremely high and is of great significance in the diagnosis of patients with pancreatic cancer and pancreatitis." (PMID 34980146, 2022). "In breast and pancreatic cancer, inhibiting EphA2 reduces VEGF expression with the resultant angiogenesis in vivo." (PMID 35747793, 2022). "The nPES assay demonstrated the ability to distinguish pancreatic cancer patients (n = 49) from pancreatitis patients (n = 48) based on a level of EphA2-EVs." (PMID 35880114, 2022). "In pancreatic cancer, an extremely aggressive tumor which accounts for about 7% of all cancer deaths in the United States, EphA2 overexpression is inversely correlated with patient survival." (PMID 34204178, 2021). "It is worth noting that the ability of EphA2 (AUC=0.94) on serum sEVs to distinguish between pancreatic cancer patients and healthy people was similar to that of CA19-9 (AUC=0.95)." (PMID 34094979, 2021). "In a non-randomised phase I/II trial (NCT04180371), the BT5528 drug (bicycle peptide targeting EphA2) is being used in combination with nivolumab for the treatment of advanced solid tumours including pancreatic cancer." (PMID 33546207, 2021). "We had previously identified EGFR as well as EPHA2 being hyperphosphorylated in pancreatic cancer and esophageal cancer, respectively." (PMID 34298619, 2021). "In an attempt to create a novel and more flexible EphA2-targeting system, we report here that proper peptide–biotin streptavidin complexes can be used to effectively target EphA2 in both breast- and pancreatic-cancer cells and tumors." (PMID 34204178, 2021). "This study provides evidence to support a conserved functional role of EphA2 in Ras-driven cell competition in epithelial tissues and suggests that EphA2 is a novel tumor suppressor in pancreatic cancer." (PMID 33891893, 2021). "Here we focused on further investigating dimeric versions of these agonistic agents in pancreatic cancer cells, compared to a dimeric natural ligand (ephrinA1-Fc) and to EphA2 knockout cells." (PMID 32397624, 2020). "For example, we previously demonstrated that earlier EphA2 targeting agonistic agents conjugated with gemcitabine had superior efficacy compared to gemcitabine alone in mice models of pancreatic cancer." (PMID 32397624, 2020). "In particular, we propose a structural model for the mechanism of receptor activation by dimeric agents and characterize the effect of most potent compounds in inducing EphA2 activation and degradation in a pancreatic cancer cell line." (PMID 32397624, 2020). "Accordingly, we found that EphA2-KO BxPC3 pancreatic cancer cells presented reduced migratory properties that are comparable to WT-cells treated with either ephrinA1-Fc or our dimeric agonistic agents." (PMID 32397624, 2020). "Nonetheless, our recent EphA2-KO data with pancreatic cancer cells suggested that EphA2 subtype alone contributes to the pro-migratory properties." (PMID 33023262, 2020). "In our recent studies, we targeted EphA2 in pancreatic cancer with agonistic agents and demonstrated that suppression of EphA2 significantly reduced cancer-cell migration in cell-based assays." (PMID 33023262, 2020).
pancreatic cancer (continued). "Rg3 effectively inhibits the formation of pancreatic cancer vasculogenic mimicry by downregulating the expression of VE-cadherin, EphA2, MMP9, and MMP2." (PMID 32733585, 2020). "In the case of pancreatic cancer, a recent study demonstrated that EphA2 is present in exosomes from gemcitabine-resistant cells." (PMID 32756339, 2020). "After a meticulous proteomics and bioinformatics screening, the anti-CD63-AuNP probe was replaced with EphA2 (anti-EphA2-AuNP) as a pancreatic-cancer-specific EV marker." (PMID 31134179, 2019). "As plasma samples from normal healthy controls (NC), pancreatitis, and pancreatic cancer patients were tested, the EphA2-EV signals were significantly higher." (PMID 31134179, 2019). "As 23 pancreatic cancer patients were evaluated pre and post neoadjuvant therapy, the EphA2-EV levels in comparison to CA19-9 more accurately reflected the treatment status for patients with good or partial therapy responses." (PMID 31134179, 2019). "At the final part of the study the EphA2-EV nPES assay was harnessed to analyze a cohort of normal control individuals (n = 48), chronic pancreatitis (n = 48), and pancreatic cancer patients (n = 49) at different stages of the disease." (PMID 31134179, 2019). "In parallel with this we have shown that both RCP and EphA2 are required for efficient invasion and metastasis in an in vivo model of pancreatic cancer, and to maintain a cell:cell repulsion phenotype in pancreatic tumour cells ex vivo." (PMID 28294115, 2017). "It is of note that eight out of nine pancreatic cancer patients exhibited soluble EphA2 fragment levels over the cutoff value." (PMID 29072678, 2017). "On the basis of the results of our present study, we propose that the soluble EphA2 fragments shed into blood are a valuable biomarker for the presence of cancer cells in patients, particularly in pancreatic carcinoma." (PMID 29072678, 2017). "Overall, specific detection of the soluble EphA2 fragment cleaved by MT1-MMP in cancer cells is likely to become a key technology of pancreatic carcinoma diagnosis using blood specimens." (PMID 29072678, 2017). "Higher concentrations of the soluble EphA2 fragment were detected in patients with gastric carcinoma (460±379 pg/ml) and pancreatic carcinoma (951±317 pg/ml)." (PMID 29072678, 2017). "Further studies on the use of EphA2 targeting agents such as YNH or 123B9 to direct chemotherapy to pancreatic cancers is therefore warranted to devise innovative and perhaps more effective therapies for this invariably fatal and aggressive cancer." (PMID 26959746, 2016). "In particular, we demonstrated that a targeted delivery strategy of Paclitaxel using these EphA2 targeting agents is more efficacious than Paclitaxel alone in xenograft models of pancreatic cancer." (PMID 26959746, 2016). "The data obtained demonstrate that in pancreatic cancer anti-tumor activity can be achieved targeting EphA2 with different mechanisms." (PMID 20130824, 2009). "The aim of the present work was to generate monoclonal antibodies to evaluate the therapeutic potential of targeting EphA2 in pancreatic tumor." (PMID 20130824, 2009). "We selected two high-affinity and highly specific EphA2 monoclonal antibodies with different in vitro properties on the human pancreatic tumor cell line MiaPaCa2." (PMID 20130824, 2009). "Stimulation with ephrinA1 produced rapid increases of EphA2 phosphorylation that were inhibited by dasatinib, although the effects on activation of downstream signalling differed among the pancreatic cancer cell lines." (PMID 18797457, 2008). "Collectively, stimulation with ligand produced rapid increases of EphA2 phosphorylation, although the effects of EphA2 activation on downstream signalling differed among the pancreatic cancer cell lines." (PMID 18797457, 2008). "EphA2 is one prominent member that is overexpressed and functionally altered in many invasive cancers, including pancreatic cancer." (PMID 18797457, 2008).
pancreatic cancer (continued). "Decreased exosomal EphA2 levels in plasma could reflect good/partial response to neoadjuvant therapy in pancreatic cancer patients." (PMID 39054529, 2024). "Additionally, compared to non-cancerous patients, significantly higher type-A receptor 2 (EphA2) levels were noted in serum exosomes of pancreatic cancer patients." (PMID 39062561, 2024). "A recent study demonstrated that exosome-mediated EphA2 may be required for the acquisition of gemcitabine resistance in pancreatic cancer cells." (PMID 37712876, 2023). "In addition, the cut-off values for EphA2-NF calculated by Youden index were 45.5 and 59.8 pg/mL for HD versus pancreatic cancer and HD + IPMN versus pancreatic cancer, respectively." (PMID 37712876, 2023). "Previous reports have shown that ligand-independent EphA2 signaling (pS897-EphA2) induced by RSK1/2 and/or AKT signaling is a trigger for pancreatic cancer chemoresistance, and the N-terminal truncated EphA2 fragment can be a transmitter at the cancer cell surface for pS897-EphA2 signaling." (PMID 37712876, 2023). "Importantly, serum EphA2-NF can improve pancreatic cancer serodiagnosis when combined with CA19-9 levels." (PMID 37712876, 2023). "Importantly, follow-up of EphA2-NF–high IPMN cases confirmed the development of pancreatic cancer and pancreatic duct dilatation." (PMID 37712876, 2023). "Furthermore, we evaluated serum EphA2-NF level as a predictive biomarker for pancreatic cancer development in patients with IPMN." (PMID 37712876, 2023). "In this study, we established a serum EphA2-NF quantitative analysis system, which was used to evaluate the potential of EphA2-NF as a new biomarker for early pancreatic cancer diagnosis and prediction of therapy response using sera from independent testing and validation cohorts." (PMID 37712876, 2023). "Furthermore, the combination of EphA2-NF and CA19-9 can improve the diagnostic accuracy of early-stage pancreatic cancer." (PMID 37712876, 2023). "Compared with CA19-9, as the conventional tumor marker for pancreatic cancer, serum EphA2-NF could diagnose approximately 50% of early-stage pancreatic cancer cases in both the test and validation cohorts." (PMID 37712876, 2023). "In pancreatic cancer, exosomal expression of Ephrin type-A receptor 2 (EphA2) could serve as a minimally-invasive predictive biomarker for responding to GEM." (PMID 33407894, 2021). "At the same time, the expression level of EphA2 on serum sEVs was also significantly increased in patients with pancreatic cancer, and the expression level of these vesicles in advanced patients (III and IV) was significantly higher than that in early patients (I and II)." (PMID 34094979, 2021). "In addition, our recent studies in a variety of pancreatic cancer cell lines, or primary pancreatic cancer tissues, demonstrated elevated EphA2 levels in all studied cases." (PMID 34204178, 2021). "For example, the fusion of EphA2-targeting peptides and paclitaxel has been an active area of investigation, in addition to a fusion of gemcitabine and an EphA2 peptide targeted to pancreatic cancer." (PMID 32492868, 2020). "In addition, our recent studies in a variety of pancreatic cancer cell lines, or primary pancreatic cancer tissues, revealed elevated EphA2 levels." (PMID 32397624, 2020). "In addition, EphA2 amplification detected in only a low percentage of cases (1 in 33 pancreatic cancer samples)." (PMID 32811512, 2020). "In addition, EphA2-Fc strongly inhibited angiogenesis and microvessel growth in vitro as well as growth in pancreatic tumor xenografts." (PMID 32811512, 2020). "Although CA19-9 is frequently used for a clinical blood test to screen for pancreatic cancer, the soluble EphA2 fragment appears to be more accurate and has the potential to replace CA19-9 or be used in a complementary manner to overcome the limitations of CA19-9." (PMID 29072678, 2017). "Western blotting data showed that this pancreatic cancer cell line highly expresses EphA2." (PMID 26959746, 2016).
pancreatic cancer (continued). "In conclusion, albeit at preliminary stages, our data support the use of these novel EphA2-targeting drug conjugates suggesting that they may provide an exciting new strategy for pancreatic cancer drug development." (PMID 26959746, 2016). "Overall, these studies provide encouraging evidence that conjugation of chemotherapy to our EphA2 targeting agents may have potential to improve clinical outcome in pancreatic cancer patients." (PMID 26959746, 2016). "Dasatinib might therefore have activity in pancreatic cancer because of EphA2 inhibition, in addition to its effects on Src." (PMID 18797457, 2008). "Treatment with dasatinib decreased EphA2 phosphorylation in BxPC-3 xenografts, suggesting that dasatinib might have activity in pancreatic cancer due to EphA2 inhibition, besides its effects on Src." (PMID 18797457, 2008). "As EphA2 is frequently overexpressed in pancreatic cancer, and selective small molecule EphA2 inhibitors are not currently available, we investigated the therapeutic potential to target EphA2 by dasatinib in several pancreatic cancer cell lines as well as in BxPC-3 xenografts." (PMID 18797457, 2008). "Using this method, the authors identified ephrin type-A receptor 2 (EphA2) as a biomarker for pancreatic cancer EVs and demonstrated that an nPES assay for EphA2-EVs could distinguish pancreatic cancer patients from those with pancreatitis and healthy individuals." (PMID 39769916, 2024). "Similarly, higher exosomes EphA2 in plasma also could predict early pancreatic cancer recurrence after surgery." (PMID 39054529, 2024). "Therefore, EphA2-NF may aid in the diagnosis of early-stage pancreatic cancer, and future studies should evaluate the use of EphA2-NF together with imaging modalities." (PMID 37712876, 2023). "Therefore pancreatic tumor cells appear to be sensitive to EphA2 targeting by different mechanisms." (PMID 20130824, 2009). "Although apoA2-ATQ/AT can diagnose pancreatic cancer in the early stages or pancreatic cancer development from IPMN, the CLIA for EphA2-NF is superior to that of apoA2-ATQ/AT." (PMID 37712876, 2023). "The mean values of serum EphA2-NF and CA19-9 were above the cut-off values for stages I and II pancreatic cancer, similar to the test cohort." (PMID 37712876, 2023). "When comparing the OS obtained from patients under standard regimens of pancreatic cancer chemotherapy with GnP and mFFX, the MST among EphA2-NF–low cases was approximately two times longer than that of EphA2-NF–high cases treated with GnP." (PMID 37712876, 2023). "Similar to the EphA2-NF values, the distribution of CA19-9 values in pancreatic cancer cases was wider than that in the other groups." (PMID 37712876, 2023). "Therefore, serum EphA2-NF, as a new biomarker for pancreatic cancer diagnosis independent of CA19-9, may improve the diagnostic accuracy in patients with Lewis-negative pancreatic cancer combined with imaging tests." (PMID 37712876, 2023). "Markosyan and his colleagues identified PTGS2 was upregulated by EPHA2, a candidate tumor intrinsic driver of immunosuppression, through TGF-β pathway in pancreatic cancer." (PMID 33718229, 2021). "Moreover, since EphA2/TGFβ/COX2 signaling in cancer cells is known to suppress the number of infiltrating T lymphocytes in pancreatic cancer, it may be possible that exosome-mediated EphA2 delivery between cancer cells further concurrently influences on cancer microenvironment." (PMID 32756339, 2020). "In this report, we detected low basal levels of EphA2 tyrosine phosphorylation in BxPC-3, PANC-1 and MIA PaCa-2 pancreatic cancer cell lines, and these were further enhanced following ligand stimulation." (PMID 18797457, 2008). "Furthermore, the AUCs using EphA2-NF, CA19-9, or EphA2-NF + CA19-9 were 0.83, 0.85, and 0.94, respectively, for early-stage pancreatic cancer (stage I/II), and 0.93, 0.91, and 0.99, respectively, for late-stage pancreatic cancer (stage III/IV)." (PMID 37712876, 2023).
pancreatic cancer (continued). "Furthermore, the combination of EphA2 and CA19-9 detected 96/97 (99.0%) patients with pancreatic cancer, 4/5 (80.0%) patients with early-stage pancreatic cancer, and 76/77 (98.7%) patients with late-stage pancreatic cancer." (PMID 37712876, 2023). "On the basis of our results, serum EphA2-NF is considered to have sufficient performance for the diagnosis of Lewis-negative pancreatic cancer, for which CA19-9 is not applicable." (PMID 37712876, 2023). "Of these, EPHA2 is particularly well characterized in PDAC with other groups recently presenting evidence of EPHA2-mediated drug resistance in pancreatic cancer cells and proposing EPHA2 as a potential biomarker or therapeutic target in pancreatic cancer." (PMID 33213062, 2020). "This suggests that the mechanism by which reduction of EphA2 expression is achieved is probably not relevant for the growth inhibition of pancreatic tumors in mice." (PMID 20130824, 2009). "In all three pancreatic cancer cell lines, low basal levels of EphA2 tyrosine phosphorylation were detected in the absence of ligand, and these showed large increases following ligand stimulation." (PMID 18797457, 2008). "As selective small molecule EphA2 inhibitors are not currently available, we investigated the therapeutic potential to target EphA2 by dasatinib in pancreatic cancer cell lines." (PMID 18797457, 2008). "Furthermore, the EphA2 N-terminus staining score was significantly reduced in pancreatic cancer compared with that in IPMN without pancreatic cancer, and was also reduced compared with that in high-grade IPMN without pancreatic cancer." (PMID 37712876, 2023). "We also found that serum-EphA2-NF could effectively predict the prognosis after chemotherapy for pancreatic cancer, which was not the case for CA19-9." (PMID 37712876, 2023). "In addition, because we did not mention the molecular mechanisms by which EphA2-NF is involved in the development of pancreatic cancer in this study, we plan to conduct basic research using molecular biological analysis." (PMID 37712876, 2023). "In summary, these results suggest that EphA2 N-terminus deletion is involved in pancreatic cancer development from IPMN and that EphA2-NF produced by cleavage can be used as a biomarker to diagnose pancreatic cancer and predict pancreatic cancer development from IPMN." (PMID 37712876, 2023). "Lastly, although the authors observed inverse correlations between EPHA2 and CTL gene signatures in human pancreatic cancer, we did not discover any consistent trends between EPHA2 and CD3E, CD8B, GZMA, GZMB, PRF1, or IFNG expression from the TCGA lung adenocarcinoma dataset." (PMID 40867322, 2025). "Finally, we combined the results of the expression levels of EphA2 N- and EphA2 C-termini in IPMN with and without pancreatic cancer according to the ASR." (PMID 37712876, 2023). "To confirm whether pancreatic cancer carcinogenesis can be detected by serum EphA2-NF, we performed ROC analysis using IPMN sera, including very early-stage pancreatic cancer that may not be detected by imaging tests because pancreatic cancer develops annually in only approximately 1% of IPMN cases." (PMID 37712876, 2023).